Y_RNA (Y RNA )
Gene: Miscellaneous RNA gene on chromosome 6 (31,778,817 to 31,778,905, reverse strand). Ensembl gene ENSG00000201555.
Homologues: Orthologues: chimpanzee Y_RNA (100% identical). Paralogues in human: RNY3 (92% identical), RNY3P1 (90% identical), Y_RNA (90% identical), Y_RNA (89% identical), Y_RNA (88% identical), Y_RNA (87% identical), Y_RNA (85% identical), RNY3P14 (84% identical), RNY3P16 (84% identical), Y_RNA (84% identical), RNY3P11 (83% identical), RNY3P4 (83% identical), and 91 more.